CCL3 (C-C motif chemokine ligand 3)
Diseases named in the same sentence as CCL3 in open-access papers (continued):
Sharing a sentence is not in itself a finding about the gene and the disease.
tumor (continued). "In vivo, Ccr5-/- CTLs that were co-transferred with WT CTLs showed impaired homing into CCL3/CCL4-secreting tumours and, in contrast to WT CTLs, did not bind fluorescent CCL3." (PMID 33046212, 2020). "Previous data demonstrate that CCL3 (MIP-1α) and CCL4 (MIP-1b) control the infiltration of the immune cells by recruiting antigen-presenting cells, including dendritic cells (DCs), to the tumor site via IFN-γ." (PMID 33302400, 2020). "Besides M‐CSF, the CC chemokines CCL2, CCL3, CCL4 and CCL5 are well‐recognized chemotactic factors for macrophage populations in the tumour." (PMID 33025708, 2020). "(D) Average speed (Left) and FMI (Right) of CTLs adjacent to tumouroids containing control or CCL3/CCL4-secreting EL4 tumour cells compared with non-cognate and SIINFEKL-pulsed cognate tumouroids pre-embedded with tumour-reactive CTLs." (PMID 33046212, 2020). "These MAMs allow the extravasation of mouse tumor cells by secreting the chemokine ligand CCL3 and CSF-1 that facilitates metastatic seeding of breast cancer cells in the lung and potentially VCAM-1 that transmits survival signals to these tumor cells." (PMID 30832375, 2019). "Further analysis showed that macrophage chemoattractants MCP-1 (CCL2) and MIP-1α (CCL3) and neutrophil chemoattractants MIP-2 (CXCL2) and KC (CXCL1) were significantly elevated, and these chemokines were secreted by K-ras activated tumor cells." (PMID 32039025, 2019). "Of note, systemic levels of CCL3 levels did not correlate with the tumor grade in our glioma patient cohort." (PMID 31847343, 2019). "Moreover, the PMo-secreted CCL3, CCL4, and CCL5 chemokines summon and activate NK cells, thus leading to further elimination of metastasizing tumor cells and prevention of lung metastasis." (PMID 30200242, 2018). "Other chemokines such as CCL2, CCL3, CCL4 promote tumour invasion and metastases." (PMID 29719625, 2018). "Exosomes derived from heat-stressed tumor cells (HS-TEX) which contain chemokines, such as CCL2, CCL3, CCL4, CCL5, and CCL20, could chemoattract and activate dendritic cells (DC) and T cells more potently." (PMID 29164149, 2017). "As the quantity and activity of TAMs could be explained by the expression of Arg1, Fizz1, Msr2, CCL3, CCL22, and so the mRNA levels of these factors in tumor tissues were detected." (PMID 29137420, 2017). "Therefore, we investigated the expression of Arg1, Fizz, Msr2, CCL3, CCL22 mRNA in tumor cells using RT-qPCR." (PMID 29137420, 2017). "Indeed, chemokines such as CCL3, CCL4, CCL5 and CXCL10 were significantly increased in tumours injected with MV-Edm." (PMID 28701757, 2017). "This indicates a CCL3 dependent recruitment of those populations to the non-irradiated tumor after irradiation." (PMID 28638385, 2017). "In addition, it is well known that CCL3, CCL4 and CCL20 are able to recruit T cells containing CTLs to the tumor site." (PMID 29079795, 2017). "The increased macrophage recruitment may be a response to the increased chemokine release by tumor cells such as CXCL-10, CCL-2, CCL3, CCL4, and CCL5." (PMID 28670313, 2017). "ELISA analysis revealed that L3TU produced ~350 pg/ml of CCL3 per 1 × 106 tumor cells in vitro over 24 h, whereas WTTU failed to secrete any detectable CCL3." (PMID 29109732, 2017). "Activated Vγ9Vδ2-T cells may secrete chemokines, such as C-C motif chemokine ligand 3 (CCL3), CCL4, C-X-C motif chemokine 10 (CXCL10), and CXCL13, to recruit αβ-T cells, B cells, NK cells, and macrophages/DCs to the tumor site." (PMID 28894450, 2017). "In addition, they can produce macrophage inflammatory protein 1-alpha (MIP-1α or CCL3), which recruits more myeloid cells into the tumor bed." (PMID 27598210, 2016). "The expression of Ccr5 and its ligands, Ccl3 and Ccl4, but not Ccl5, were markedly increased in tumor sites 7 days after the injection." (PMID 27340784, 2016).
tumor (continued). "Our PCR array data showed that both M1-related genes (Ccl2, Ccl3, Ccl4, Ccl5, Il12b, Il1b and Ccl1) and M2-related genes (Il10, Tgfb2 and Il1rn) were significantly upregulated in NM11-shsST2 tumours compared with NM11-shCont tumours." (PMID 27882929, 2016). "Likewise, in an experimental melanoma model, tumor-infiltrating Tregs expressed CCR5 and preferentially migrated toward its ligands CCL3, CCL4, and CCL5, which were elaborated by tumor-infiltrating myeloid-derived suppressor cells (MDSCs)." (PMID 26217588, 2015). "Furthermore, the chemokines CCL3 and CCL4 production from tumor cells were also found to be attenuated by ibrutinib treatment." (PMID 24693884, 2014). "Several CC chemokine members, including CCL2 (MCP-1), CCL3 (MIP-1α), CCL5 (RANTES), CCL7 (MCP-3), CCL8 (MCP-2), CCL17 (TARC) CCL 20 (MIP-3α), CCL22 (MDC) and CCL23 (MPIF-1), are produced mainly by tumor infiltrating lymphocytes (TIL) and monocytes, and some of them also by cancer cells." (PMID 24213462, 2012). "Indeed, we found that CD277 is up-regulated in monocyte-derived DCs by multiple inflammatory cytokines and hypoxia-induced mediators commonly found in the tumor microenvironment, including VEGF, and CCL3 and, to a lesser extent, IL-6." (PMID 21113407, 2010). "EpCAM, IL8, CXCL10/IP10, CCL3/MIP-1α, CCL4/MIP-1β, CCL15/MIP-1δ, PDGFR-B protein were found to be expressed predominantly in tumours only, suggesting that they could be involved in the later stages of gastric tumorigenesis." (PMID 21092330, 2010). "Tumor-resident CD8+ T cells, polarized by such a type 1 cytokine–rich environment, downregulate tumor-specific immune responses by facilitating the local migration of CD4+Foxp3+ Tregs through the accumulation of several CCR5-specific cytokines, such as MIP-1α (CCL3) and MIP-1β (CCL4)." (PMID 40553564, 2025). "N1-type neutrophils, characterized by their anti-tumor phenotype, exhibit hypersegmented nuclei and high expression levels of factors such as tumor necrosis factor-α (TNF-α), intercellular adhesion molecule-1 (ICAM-1), vascular cell adhesion molecule-1 (VCAM-1), and CCL3." (PMID 40282474, 2025). "Cisplatin-triggered ferroptotic tumor cells reprogram TANs toward an N1-like phenotype, characterized by the upregulation of cytotoxic effectors such as TNF-α, granzyme B, and NE, as well as chemokines and cytokines including CCL2, CCL3, CXCL9, CXCL10, CXCL11, IL-12A, and IL-12B." (PMID 40805288, 2025). "The presence of tumor cells was sufficient to upregulate several other pro-inflammatory cytokines and chemokines, including tumor necrosis factor alpha, IL-6, chemokine C-C motif ligand 3 (CCL3), and CCL4, regardless of anti-PD-L1 treatment." (PMID 41050935, 2025). "In addition, the IT L1 peptide/polyI:C-treated mice displayed an increase in CXCL10, CCL2, CCL3 and CCL4 and GM-CSF in the tumor lysate which could be involved in the recruitment, retention and maturation of myeloid and lymphoid cells in the tumor." (PMID 40280970, 2025). "Moreover, the expression of chemokines such as CCL3,CCL4, and CCL5 may influence T cell recruitment and localization, further exacerbating the immunosuppressive state in the tumor microenvironment." (PMID 41394809, 2025). "CCL3/4 were reported to facilitate the infiltrating of inhibitive CCR5+ MDSCs, and concurrent blocking CCR5/CCR5‐ligand and PD1/PD‐L1 axes could enhance efficacy and prolong survival in preclinical tumor models." (PMID 39974662, 2025). "Additionally, the characteristic expression profile of this cell subgroup included multiple myeloid cell activation markers, such as IL1RN, CXCL8, CCL20, and the chemokines CCL3 and SPP1, indicating the activated state of myeloid cells in the tumour microenvironment." (PMID 40539065, 2025). "Notably, CCL3 exemplifies the dual role of cytokines in CRC progression: while it recruits immune cells via chemotaxis, its overexpression activates the TRAF6/NF-κB axis to promote tumor cell survival and invasion." (PMID 40963625, 2025).
tumor (continued). "Not less important, physical exercise induces shear stress in the tumor vascular wall and may modulate angiogenic factors (e.g., VECF-A, VEGF-R2, CD31) and the chemokine CCL3 in endothelial cells, which are strongly related with stimulating physiologic angiogenesis stimulation." (PMID 39769501, 2024). "Immunofluorescence staining confirmed that the expression of chemokines CCL3, CCL4 and CCL5 and the cytokines IL-12, IL-15 and IL-18 by KCs in the liver of Clec4fcreId3f/f mice was reduced or abolished at the tumour margin and in the tumour in comparison to in the littermate controls." (PMID 38326607, 2024). "Notably, the C2-CD8 cluster was characterized by low expression of cytokines/chemokines (CCL3, CCL4L2, XCL1, and XCL2), which might hinder infiltration of effector CD8 T/NK cells and DCs into the peritoneum for their anti-tumor functions." (PMID 36788228, 2023). "In addition, MDSC could interplay with SPP1+ TAMs via the LR pair CCL3/CCL3L3-CCR1, which might facilitate the recruitment of SPP1+ TAMs in tumor tissue." (PMID 37475874, 2023). "Finally, we confirmed both in vitro and in vivo that CCL3 could activate VIRMA and its critical downstream target SIRT1, which fuels tumor metastasis in ICC." (PMID 36691046, 2023). "Simvastatin could decrease CCL3 expression from cancer cells and ICAM-1, VCAM1, IL-6, and CCL2 expression from CaMSCs, disrupting the crosstalk of the cancer cells and tumor microenvironments (TME) and inhibiting tumor progression." (PMID 36430409, 2022). "In contrast, N1 TANs produce chemokines, such as C-C motif chemokine ligand 3 (CCL3, CXCL9, CXCL10), to recruit CD8+ T cells to TME and secrete cytokines (e.g., IL-12, TNF-α, and GM-CSF) to activatethe cytotoxicity of CD8+ T cells, thus providing anti-tumor effect." (PMID 34359674, 2021). "Furthermore, tumor hyperthermia potentiated immune system responses through release of exosomes containing chemokines (CCL2, CCL3, CCL4, CCL5, and CCL20), HSPs, and tumor antigens to the antigen-presenting cells and facilitated tumor cell attack and tumor cell surface modulation." (PMID 34337063, 2021). "Also in contrast to CCL3/MIP-1α, significant differences were observed only in tumors from old stressed mice, which had higher tumor CCL4/MIP-1β levels than tumors in young non-stressed mice (p<0.05)." (PMID 34604038, 2021). "Also, a role for “patrolling” monocytes (PMo) in regulating NK cell anti-tumor activity has been delineated in a murine model of lung cancer where PMo induced NK cell recruitment through secretion of high levels of CCL3, CCL4, CCL5 and their activation in the tumor site." (PMID 34975880, 2021). "Similarly, PMN-MDSC and neutrophils are also recruited to tumours by CCL2 and CCL3." (PMID 32121014, 2020). "However, the fundamental mechanisms of CCL3 in the tumor microenvironment and the signaling pathways are not well known." (PMID 32349303, 2020). "Furthermore, as cytokines can assist tumor progression, targeting IL-4, IL-13, IL-10, TGF-β, and CXCL5 or enhancing IFN-γ and some chemokines (e.g., CCL2, CCL3, CXCL9, CXCL10) may inhibit tumor invasion and metastasis." (PMID 32346605, 2020). "M-MDSC and inflammatory monocytes are recruited to tumours through a CCL1, CCL2, and CCL5-induced chemokine cascade that is propagated by cancer cells and has been found to be retained within primary tumours by CCL3 produced via CCR-2 activated mechanism in metastasis-associated macrophages." (PMID 32121014, 2020). "With this in mind, the higher IL-17 production observed by flow cytometry and expression of the inflammatory genes RSG1, CCL3, and CCL4 revealed by our scRNA-seq data could support a pro-tumorigenic role of CD39 expression in tumor-infiltrating MAIT cells in CRC." (PMID 33205061, 2020).
tumor (continued). "Interestingly, studies that compared tumours infiltrated by leukocytes (‘hot’) to those that excluded immune cell infiltration (‘cold’) identified more abundant CCL3, CCL4, and CCL5 in hot tumours, including via single-cell transcriptomics that ascribed their expression to CD8+ T cells." (PMID 33046212, 2020). "However, the comparative lack of production of pro-inflammatory chemokines (e.g. CCL3, CCL4) and absence of lymphocytes in primary tissue are consistent with the failure of DIPG-associated macrophages to trigger an effective anti-tumor immune response." (PMID 29954445, 2018). "Since the gMDSCs derived from metastatic 4T1 tumour-bearing animals were able to suppress the EMT-related genes and also induce distinct set of genes; S100A9, MMP8, S100A8, WFDC21, LYZ2, FPR1, CCL3, TGFb2, we reasoned whether these genes could be specific for metastatic/aggressive behaviour." (PMID 28382931, 2017). "Ccl2 and Ccl3 mRNA levels were not increased in tumours from HFD mice." (PMID 27708283, 2016). "In our model, the anti-CCL2 antibody treatment reduces CCL3 expression in MAMs but inhibition rate is only 40% compared with IgG treatment, suggesting that factors other than CCL2 from cancer cells and/or tumor microenvironment also involve in CCL3 secretion from MAMs." (PMID 26275794, 2015). "Furthermore, a recent report showed that CCL3 was necessary (but not sufficient) for tumor rejection and efficient DCs migration to lymph nodes." (PMID 26494531, 2015). "Furthermore, α-TEA treatment modulated the tumor microenvironment in a proinflammatory fashion, as we found significantly higher IL-6 and CCL5 levels and a trend toward higher levels of other proinflammatory mediators (IL-1β, CCL2, CCL3, CCL4)." (PMID 21232138, 2011). "Hence, CAR-NK-92 cells exert its tumor killing mainly through (i) granule-mediated cytotoxicity via perforin and granzymes; (ii) death receptor-mediated apoptosis, involving FasL and TRAIL; and (iii) the secretion of proinflammatory cytokines and chemokines, e.g., TNF-α, IFN-Ɣ, and CCL3." (PMID 34337077, 2021). "Thus, to examine whether there are common tumor-promoting factors between parent and resistant cells that enhance neutrophil survival, we tested the expression of pro-inflammatory factors such as IL-1β, CCL2, CCL3, CCL4, IL23, and iNOS in neutrophils." (PMID 33049964, 2020). "Consistently, the production and expression of the chemokines CXCL1 and CXCL2, but not CCL3 and CCL5, were significantly upregulated in serum and tumor-infiltrating neutrophils from Arnt−/− mice." (PMID 36859266, 2023). "Compared to normal tissue from non-cancer patients, the CCL3, CCL4 and CXCL2 expressions were upregulated in both tumor and tumor-adjacent tissue, while CCL19 was upregulated solely in tumor-adjacent tissue." (PMID 34885960, 2021). "CCL3, CCL4, IL-1α and IL-12/IL23p40 were highest in individuals with no adverse features of tumor biology, whereas levels of Tie2 and VEGF were lowest in this cohort." (PMID 33202734, 2020). "There are no previous data on CCL2, CCL3 or CCL4 in PitNETs, but these chemokines are involved in tumour growth and invasion in other tumours, as well as in immune cell chemotaxis in cancer." (PMID 31703742, 2019). "However, the participation of CCL3/CCR5 axis in established tumour could not be clearly defined." (PMID 28881626, 2017). "However, other CCLs, including CCL2, CCL3, CCL11, CCL26, and CCL28, did not exhibit significant changes in expression during tumor progression." (PMID 39859340, 2025). "When compared to exosomes from tumor cells without heat stress (TEX), heat-stressed tumor cell-derived exosomes (HS-TEX) had more chemokines (CCL2, CCL3, CCL4, CCL5, and CCL20), HSPs (HSP60, HSC70, HSP70, and HSP90), and adhesion molecules (e.g., CD54 and CD86)." (PMID 35158999, 2022). "Interestingly, the TCM from the poorly immunogenic tumor CT26 and recombinant IL6 alone did not modulate CCL3 or CCL4 production." (PMID 35064009, 2022).
tumor (continued). "The quantitative PCR results were consistent with the transcriptome results, showing that the expression of CCL2, CCL3, CCL5, and CXCL9, but not CCL17 or CCL22, was markedly higher in 1.5 mg/kg AAGL-treated tumor-bearing mouse livers than in those of control mice." (PMID 33710817, 2021). "Because we have observed reduced SCC formation in the CCL3-/- mice, we then evaluated whether the expression of angiogenic factors, cytokines and ECM components would be consistently diminished in the tumour milieu by the absence of CCL3." (PMID 28881626, 2017). "What is interesting in this study is that a low level (500 ng) of CCL3 has an effect, while high amounts (5000 ng) do not, thus suggesting that the effects of chemokines on the recruitment and/or activation of CD8 T cells may partly depend on the quantity produced at the tumor site." (PMID 36429101, 2022).